MPIG6B (megakaryocyte and platelet inhibitory receptor G6b)
Description:
Inhibitory receptor that acts as a critical regulator of hematopoietic lineage differentiation, megakaryocyte function and platelet production. Inhibits platelet aggregation and activation by agonists such as ADP and collagen-related peptide. This regulation of megakaryocate function as well as platelet production ann activation is done through the inhibition (via the 2 ITIM motifs) of the receptors CLEC1B and GP6:FcRgamma signaling. Appears to operate in a calcium-independent manner. Isoform B, displayed in this entry, is the only isoform to contain both a transmembrane region and 2 immunoreceptor tyrosine-based inhibitor motifs (ITIMs) and, thus, the only one which probably has a role of inhibitory receptor. Isoform A may be the activating counterpart of isoform B.
Synonyms: C6orf25; G6B; G6B-B; NG31; THAMY
Tractability: Antibody: UniProt places it where antibodies can reach, with high confidence; its Gene Ontology location is reachable by antibodies, with high confidence; UniProt predicts a signal peptide or a membrane-spanning region.
Gene: Protein-coding gene on chromosome 6 (31,718,594 to 31,726,714, forward strand). Ensembl gene ENSG00000204420.
Subcellular location: Endoplasmic reticulum (Isoform E); Golgi apparatus; Endoplasmic reticulum (Isoform D); Cell membrane (Isoform B); Cell membrane (Isoform A)
Subcellular location (Human Protein Atlas): Golgi apparatus; Cytosol; Endoplasmic reticulum; Nucleoplasm; Plasma membrane
Pathways (Reactome):
Hemostasis: GPVI-mediated activation cascade
Gene Ontology:
Molecular function: protein binding
Biological process: erythrocyte differentiation; megakaryocyte differentiation; negative regulation of signal transduction; blood coagulation; integrin-mediated signaling pathway; megakaryocyte development; platelet formation
Cellular component: endoplasmic reticulum; Golgi apparatus; plasma membrane; membrane
Genetic constraint (gnomAD): Loss-of-function variants: 22 observed, 24.62 expected, observed/expected ratio (o/e) 0.89, 90% interval 0.64 to 1.28. The upper end of that interval is the gene's LOEUF score, 1.28, which puts it in group 5 of 6, group 1 being the genes least tolerant of losing a copy. Missense variants: 301 observed, 329.5 expected, observed/expected ratio (o/e) 0.91, 90% interval 0.83 to 1. Synonymous variants: 136 observed, 143.66 expected, observed/expected ratio (o/e) 0.95, 90% interval 0.82 to 1.09.
Gene-disease validity (ClinGen):
ClinGen rates the evidence that MPIG6B causes each of these diseases.
thrombocytopenia, anemia, and myelofibrosis (autosomal recessive): Definitive.
Homologues: Orthologues: macaque MPIG6B (98% identical), chimpanzee MPIG6B (95% identical), pig MPIG6B (75% identical), rat Mpig6b (73% identical), mouse Mpig6b (71% identical), dog MPIG6B (68% identical), rabbit MPIG6B (64% identical), guinea pig MPIG6B (61% identical).
Diseases named in the same sentence as MPIG6B in open-access papers:
MPIG6B is named in the same sentence as 43 diseases in open-access papers, as found by Europe PMC text mining. Sharing a sentence is not in itself a finding about the gene and the disease. The quoted sentences say what the papers report.
myelofibrosis (8 papers, 2019 to 2024). A partial or complete replacement of the bone marrow stroma by fibrous tissue. "Mice with a genomic deletion of the entire MPIG6B locus develop severe macrothrombocytopenia and myelofibrosis, which has a human homologous as null mutations in MPIG6B." (PMID 35887218, 2022). "Thrombocytopenia, anemia, and myelofibrosis (THAMY) is an exceptionally rare autosomal recessive inherited disorder that arises from pathogenic variations in the megakaryocyte platelet inhibitor G6B (MPIG6B) gene." (PMID 38481905, 2024). "Importantly, null and loss-of-function mutations in human G6b-B have been reported to recapitulate key features of the Mpig6b KO and loss-of-function mouse phenotypes, including a severe macrothrombocytopenia, MK clusters in the bone marrow and myelofibrosis." (PMID 31436532, 2019). "The oncogenic and immunogenic functions of MPIG6B are poorly understood, but a recent study identified that this molecule is essential for the induction of megakaryocytes, which are responsible for myelofibrosis." (PMID 39867897, 2024).
COVID-19 (2 papers, 2022 to 2023). A disease caused by infection with severe acute respiratory syndrome coronavirus 2. "Eight genes associated with platelet activation and pro-thrombosis were upregulated in COVID-19 patients: MPIG6B, HBB, HPSE, CD40LG, STXBP3, CLEC1B, TFPI and GNAS." (PMID 35477940, 2022).
infection (3 papers, 2020 to 2024). The state of being infected such as from the introduction of a foreign agent such as serum, vaccine, antigenic substance or organism. "The importance of these results lies in the validation of TFF1, GSTA5, HSPA6, FOS, MPIG6B, F2 and HP not only as key markers for the presence of infection but also for their specificity in differentiating between various Mpox strains." (PMID 39456924, 2024).
MPIG6B also shares sentences with these, for which no sentence is quoted: tumor (8 papers); autoimmune disease (2); autoimmune hepatitis (2); autoimmune thyroid disease (2); breast carcinoma (2); epithelial ovarian cancer (2); hepatocellular carcinoma (2); leukemia (2); Macrothrombocytopenia (2); Thrombocytopenia (2); viral infection (2); acute myeloid leukemia (1); allergic asthma (1); allergic reactions (1); anemia (1); atherosclerosis (1); cancer (1); cardiovascular disease (1); colorectal cancer (1); dendritic cell sarcoma (1); Diabetes (1); endometriosis (1); Graves disease (1); HIV-1 infection (1); Hodgkins lymphoma (1); infertile (1); intestinal infection (1); lymphoma (1); mantle cell lymphoma (1); marginal zone lymphoma (1).
A further 10 diseases each share a sentence with MPIG6B in 1 paper.